SOCS1 (suppressor of cytokine signaling 1)
Diseases named in the same sentence as SOCS1 in open-access papers (continued):
Sharing a sentence is not in itself a finding about the gene and the disease.
infection (continued). "The results showed that the expression of SOCS3 significantly increased at 12 h, 24 h, and 36 h after infection, and SOCS1 protein levels increased at 36 h after infection, which was consistent with SOCS mRNA results." (PMID 32149091, 2020). "The Irf1 and Stat1 contribute to the control of T. gondii by regulating the expression of factors essential for the host to resist infection, such as Socs1, Ciita, and NOS2." (PMID 33193165, 2020). "In contrast, there was a trend towards a decreased expression of SOCS1 mRNA expression following RSVA2 infection in cells treated with MEKi, and this despite an elevated IFN response in these cells compared to RSVA2 alone." (PMID 31319869, 2019). "In conclusion, we report that TLR3-TRAF-NF-κB signaling pathway play a role in the induction of SOCS1 that counteracts the antiviral effect of IFN-γ during MHV-68 infection." (PMID 30075008, 2018). "To address this issue, we isolated pDCs from YM-infected WT and gene deficient (Aim2−/−, Nlrp3−/−, Casp1−/−, Il1r1−/−, and Mavs−/−) mice at 18 h post YM infection and assessed mRNA expression levels of SOCS1, IFN-α and IFN-β." (PMID 30470758, 2018). "In the process of DENV ADE infection, the expression levels of the SOCS1, SOCS3, RIG-1 and ISG56 genes was found to be different (≥2) comparing to the levels during DENV-3 direct infection." (PMID 29566761, 2018). "SOCS1 also promotes mycobacterial growth in macrophages by blocking IFN-γ secretion in response to IL-12 induced by the infection." (PMID 29312162, 2017). "Others have demonstrated that MCMV infection in macrophages in vitro causes an increase in SOCS1 and SOCS3 mRNA expression levels from 2 to 24 hours after infection." (PMID 28182772, 2017). "Productive SG-MCMV infection of MEFs produced similar temporal patterns of SOCS1 and SOCS3 mRNA expression to those found in IC-21 cells." (PMID 28182772, 2017). "Overexpression of SOCS1 has been reported to have a proviral effect in infection and replication for viruses such as HCV, herpes simplex virus 1 (HSV-1) and vaccinia virus." (PMID 29235573, 2017). "An altered balance of SOCS1/3 expression in monocytes and/or macrophages has been described in several human infections and disease states." (PMID 26579124, 2015). "SOCS1 has been shown to be an influenza virus-induced virulence factor that enhances infection of cells." (PMID 26617608, 2015). "For three target transfections (SOCS1 siRNA #1, #2, and #3), SOCS1 protein levels reduced to 25–75 % of their original level in DCs, and SOCS1 siRNA #2 infection in particular was most effective, exhibiting a 75 % reduction." (PMID 25381480, 2015). "The results indicated that SOCS1 siRNA and GV248 were not toxic to DCs Trypan blue exclusion also confirmed that DCs were viable after infection by SOCS1 siRNA or GV248." (PMID 25381480, 2015). "Recently, it has been demonstrated that influenza virus-induced SOCS1 inhibits the phosphorylation of STAT1 at early stages of infection." (PMID 26206138, 2015). "In order to obtain some insight into the ability of the SOCS1 antagonist to protect mice against infection, we focused on several parameters that reflect the degree of morbidity." (PMID 26617608, 2015). "The LysM-cre-Socs1fl/fl mice also exhibited less infection-induced lung inflammation than did the SOCS1-KO animals after the initial acute phase of infection." (PMID 26579124, 2015). "Our experiments demonstrated that IAV-provoked STAT1 phosphorylation at the early stage of infection was inhibited by the virus-induced SOCS-1." (PMID 24391501, 2014). "The mRNA level of SOCS-1 was significantly up-regulated at early stages and began to reduce at late stages of infection, but its protein level was consistently increased." (PMID 24391501, 2014). "But, our microarray data from the murine macrophage RAW264.7 cell line shows that pre-infection with RH(I) parasites can still inhibit IFNγ induced Socs1 transcript by two-fold." (PMID 23240025, 2012).
infection (continued). "Increased SOCS expression was also confirmed at the protein level since SOCS1 expression was increased at 60 minutes post-infection whilst SOCS3 expression progressively increased from 20 to 60 minutes post-infection." (PMID 20689596, 2010). "A predominant Th1 immune response was observed during infection, as 6 of 11 investigated Th1 associated genes, including TNF, IFNG, and some IFNG-signaling responsive genes (SOCS1, STAT1, WARS and IRF1), were strongly up-regulated at 24 hpi and/or 48 hpi." (PMID 18811943, 2008). "While SOCS-3 mRNA is strongly and transiently elevated in the early phases of infection, SOCS-1 gene transcription is only significantly induced 15 h p.i.." (PMID 18989459, 2008). "SOCS-1 is known to inhibit the IFN-γ-dependent killing of Leishmania parasites, because macrophages from SOCS-1 null mice require 100-fold less IFN-γ to clear infection." (PMID 15788098, 2005). "As IEI with severe immune dysregulation and potentially life-threatening infections and malignant diseases, severely affected SOCS1 patients might be eligible for HSCT." (PMID 38711523, 2024). "SOCS1 expression was assessed at various time intervals during BJ05/H1N1 infection in A549 cells." (PMID 38435118, 2024). "SOCS1 at the intersection of metaflammation and infection-induced inflammation could thereby balance a tissue-specific disease outcome." (PMID 39284830, 2024). "SARS-CoV-2 suppresses the host immune response by activating SOCS1 or SOCS3 early in infection." (PMID 38792727, 2024). "Soni and Singh (2021a) demonstrated that peptide-based immuno-regulatory circuits have been developed to regulate the function of Suppressor Of Cytokine Signaling 1 (SOCS1), which can restore pro-inflammatory cytokine expression during infection, using synthetic biology." (PMID 38362504, 2024). "Densitometric analysis identifies the ratio of SOCS1/SOCS3 as 3:2 post one hour of infection." (PMID 35011356, 2021). "Indeed, SOCS-1 has demonstrated a detrimental impact in different infections, including viral, fungal, parasitic, and bacterial infections." (PMID 33690673, 2021). "We speculate that SOCS-1 could be inhibiting the activation of different IRFs, such as IRF7 and IRF3, but more studies are needed to address further the potential mechanisms of SOCS-1 mediated IFNα/β production and/or signaling during infections." (PMID 33690673, 2021). "Since SOCS-1 expression is increased in the skin of infected hyperglycemic mice, we asked whether the infection in hyperglycemic mice is characterized by an overall decrease in genes involved in IFN responses." (PMID 33690673, 2021). "Together, our work demonstrates a previously undocumented detrimental role for SOCS1-dependent skin host defense and suggests that blocking SOCS-1 might enable the host to efficiently control infection in both homeostatic and hyperglycemic conditions." (PMID 33690673, 2021). "Furthermore, SOCS1 has also been shown to be an influenza virus-induced virulence factor that enhances the infection of cells; therefore it has been targeted through the antagonist to treat infection in C57BL/6 mice." (PMID 35011356, 2021). "This increases the likelihood that SGPV may inhibit SOCS-1 expression as a counteractive mechanisms in the early phase of infection, and this hypothesis will be subject to our further study." (PMID 33013908, 2020). "We showed that PEDV significantly induced the expression of SOCS1 at the late stage of infection." (PMID 32574254, 2020). "The underlying consequence for the induction of SOCS1 and SOCS3 by Chlamydia may be a mechanistic ploy to limit its inflammation during early infection for perpetuation and survival in the host." (PMID 32684836, 2020). "Interestingly, expression of anti-inflammatory transcripts such as transforming growth factor beta (TGF-β) and IL-10 was found to be similar between D355A and wild-type infection, while others, such as SOCS1, were found to be significantly decreased." (PMID 33262258, 2020).
infection (continued). "Moreover, genes such as Ifr9, Ifr8, Ifr7, CSF2RA, STAT1, and STAT2 were expressed to a greater extent in the PmQ infection group than PmCQ2, and Il22, Il6, Nos2, Ccl4, Ccl5, Ifr1, Socs1, and Socs3 were increased only in PmQ infected chickens rather than PmCQ2." (PMID 32851030, 2020). "It is worth noting that a high expression level of goose SOCS1 (goSOCS1) was detected after infection with high viral load of Duck Tembusu virus (DTMUV) in vitro and in vivo, which suggests that goSOCS1 may be related to innate and adaptive antiviral immunity." (PMID 33072096, 2020). "We have not seen increased infection susceptibility in the SOCS1 mutant patients, but this has to be confirmed in larger cohorts." (PMID 33087723, 2020). "The upregulation of PIAS3 and SOCS1 and the significant degradation of unSTAT3 at the later stage of infection may partially explain the reduced expression of STAT3 target genes in the late stage of EV71 infection." (PMID 31575039, 2019). "By identifying the cellular factors that negatively regulate JAK-STAT1 signaling, we revealed that the infection of BMMs by MHV-68 induces the expression of suppressor of cytokine signaling 1 (SOCS1) and that depletion of SOCS1 restores the inhibitory effect of IFN-γ on virus replication." (PMID 30075008, 2018). "This is a characteristic of infection immunity in infection with T. gondii in the central nervous system, and SOCS1, a negative regulator of toxoplasmic encephalitis, may play a role in the increase in Arg1 levels to suppress NO production." (PMID 29459868, 2018). "Similarly, the results of western blot analysis showed an increase in SOCS1 expression during the infection period." (PMID 29459868, 2018). "Accordingly, we found increased RNA abundance of Arg1, Socs1, Sra1, Saa1, Ciita, Marco, Mgl2, Cd209d, Cd209e, Cd209f, Ccl1, Ccl11, Ccl17, Ccl19, Ccl20, Ccl22, and Ccl24 genes in Stat2−/− mice when compared to WT mice during super-infection." (PMID 30337919, 2018). "Conversely, 100% of the buffer-treated NOD and SOCS1-tg mice were viraemic on day 3 post infection." (PMID 29151123, 2018). "Because UV-inactivated MCMV failed significantly to stimulate SOCS1 and SOCS3 expression at early time points following infection of IC-21 mouse macrophages, we next investigated SOCS1 and SOCS3 mRNA expression later during MCMV infection (72 hpi) with or without the antiviral drug GCV." (PMID 28182772, 2017). "SOCS1, encoding Suppressor of cytokine signaling 1, which is induced by STAT1 activation in response to cytokine stimulation, was induced early in infection (6 h), followed by an active downregulation from 6 to 16 h of infection." (PMID 28993767, 2017). "Interestingly, the virus-induced SOCS-1 expression was cytokine-independent at early stage of infection both in vitro and in vivo." (PMID 24391501, 2014). "In contrast, at the resolution phase of infection, IL-10 level was slightly increased in SOCS1−/−IFN-γ−/− mice relative to the low levels in WT and IFN-γ−/− mice, which may contribute to the attenuation of lung inflammation after viral clearance." (PMID 25500584, 2014). "Expression of SOCS-1 protein was consistently increased during 3 days of infection." (PMID 24391501, 2014). "However, increased IFN-λ further induces the expression of SOCS-1 at late stage of infection, which in turn, inhibits the activation of JAK-STAT signaling." (PMID 24391501, 2014). "Similarly, expression of several genes in the canonical IFN signaling pathway, including Ifng, Jak2, Stat1, Stat2, Socs1, Irf1, Irf9, Tap1, Ifitm1, Psmb8, Ifi35, Gas1 and Fit3 were up-regulated during infection by the mutant strain." (PMID 25201772, 2014). "Costimulatory molecules (CD80, CD86, CD40, GITR, and ICOS), adhesion molecules (VCAM-1 and P-selectin), and signaling molecules involved in cytokine regulation (Tbx21 and Socs1) were also increased with Hb infection and decreased with anti-IL-7Rα M595 treatment in a dose-dependent manner." (PMID 23057802, 2012).
infection (continued). "In addition, a higher level of SOCS1 mRNA expression was evident at 48 h pi compared to similar infection at 24 h pi despite a significantly (p < 0.05) lower N gene copy compared to WT or ΔG virus infected cells." (PMID 18851747, 2008). "At 24 h pi, SOCS1 protein expression levels were similar following infection with RSV or RSV mutant viruses; however SOCS3 protein expression was significantly (p < 0.05) higher in ΔG virus infected cells compared to WT infected cells, and substantially higher compared to ΔNS/2 virus infected cells." (PMID 18851747, 2008). "We then tested whether GATA-3 and SOCS-1 are up-regulated by live infection with B. malayi larvae in vivo." (PMID 15788098, 2005). "Additionally, when we compared infection in HIF-α deficient macrophages compared to HIF-α competent infected macrophages, Socs1 and Mevf were strongly downregulated suggesting that HIF-α mediates the expression of Socs1 and Mevf during L. major infection." (PMID 40191198, 2025). "Genes linked to STAT3 during infection were associated with GO terms such as regulation of cell proliferation (CCND1, JUNB), negative regulation of apoptosis (MCL-1, NFKB1), cytokine-mediated signaling pathway (IL10RA, SOCS1), and immune system process (CRK, IRF9)." (PMID 41115066, 2025). "However, triggers like infections may easily tip this balance, as reported in two previously reported SOCS1+/- patients with autoimmune cytopenia." (PMID 34421895, 2021). "This study revealed that infection with DHAV-1 strain CH60 is associated with enhanced type I and II interferon responses, activated innate immune responses, elevated levels of suppressor of cytokine signaling 1 and 3 (SOCS1 and SOCS3) accompanied with abnormalities in multiple metabolic pathways." (PMID 30197639, 2018). "Enhanced viral clearance in SOCS1−/−IFN-γ−/− mice coincided with a rapid onset of adaptive immune responses during acute infection, while their reduced lung injury was associated with decreased inflammatory cell infiltration at the resolution phase of infection." (PMID 25500584, 2014). "Comparing infection-induced TCRab+ T cells, adults exhibited higher average STAT3, SOCS1, and SOCS3 expression, whereas STAT1 and STAT2 were elevated in cells from infected children, highlighting divergent IFN signaling with age." (PMID 40834853, 2025). "In the context of EBV, the virus upregulates SOCS1 and SOCS3 during latent and lytic phases of infection, likely through viral protein‐induced activation of host STAT3, which enhances SOCS transcription and inhibits downstream antiviral signaling." (PMID 40844207, 2025). "This elevated SOCS1 and SOCS3 expression contributes to leptin and insulin resistance in immune cells, impairing their ability to respond to infection effectively." (PMID 40844207, 2025). "We identified important genes DE in both our in vitro and in vivo infection models consistent with previous studies, namely, TLR3, IFIH1 (MDA5), SOCS1, OASL, DDX60, STAT1, MX1, CMPK2, LY96 (MD-2), STAT1, STAT2, TRIM25, IRF7, and IFIT5." (PMID 38675946, 2024). "SOCS1 expression was found to be upregulated in a time-dependent manner in A549 cells infected with BJ05/H1N1, particularly in the early stages of infection." (PMID 38435118, 2024). "The DEGs involved in amino acid biosynthesis and energy metabolic processes were GOT1, CBSL, SOCS1, LPL and STC2, and their expressions were largely down‐regulated in response to H37Rv infection." (PMID 34632719, 2021). "Herein, the expression of SOCS1 and SOCS3 in the lungs of co-infected mice was much higher than that in individual infection groups and the mock group." (PMID 33968006, 2021). "Out of the four Jak-STAT signaling molecules (suppressor of cytokine signaling 1 [SOCS1], SOCS3, STAT1, and STAT4) analyzed in this study, only the STAT1 gene was significantly upregulated (36 to 48 hpi) in ALI-PRECs following infection with PHEV." (PMID 34935443, 2021).
infection (continued). "In this study, only SOCS-1 showed a cumulative effect, and its expression upon ‘IVA infection of IFN-λ stimulated cells’ was threefold higher compared to ‘stimulated, uninfected’ cells." (PMID 34452467, 2021). "A biphasic pattern of SOCS mRNA production was observed with early SOCS1 and SOCS3 mRNA upregulation occurring before immediate early virus gene expression followed later by SOCS1 and SOCS3 mRNA upregulation at 3 days post-infection." (PMID 34358000, 2021). "Intriguingly, miR-30c has also been involved in the infection by Porcine epidemic diarrhea virus (PEDV), a member of the Alphacoronavirus family: the virus engages the SOCS1/miR-30c axis to escape IFN-l-mediated antiviral immune responses." (PMID 34163530, 2021). "The administration of IFN-λ1 generally led to more powerful expression of the considered genes, including MxA, Rig-1, and SOCS-1, which, in general, increased upon IVA infection." (PMID 34452467, 2021). "Western blot data depicted increased expression of SOCS1 and SOCS3 protein during infection which further got enhanced in presence of IL6 treatment." (PMID 35011356, 2021). "The expression of SOCS1 and SOCS3 genes was quantified by qRT-PCR following MR766 or PRVABC59 infection." (PMID 32120897, 2020). "The qRT-PCR results indicated a time-dependent elevation of SOCS1 and SOCS3 mRNA expression levels in response to both MR766 and PRVABC59 infections." (PMID 32120897, 2020). "Multiple viruses promote their survival by inducing SOCS1 and/or SOCS3 protein expression following infection." (PMID 32192194, 2020). "Within 6 h post-infection, HSV-1 induced both SOCS1/3 expression, which inhibited the phosphorylation of STAT1." (PMID 31861450, 2019). "Transcriptional stimulation of host SOCS1 and SOCS3 was also found in skin samples of MDV-infected chickens at 20 and 30 days post-infection." (PMID 31031749, 2019). "Herpes simplex virus type 1 (HSV-1) induces both SOCS1 and SOCS3 to block type I IFN at early infection stage within 6 h." (PMID 31861450, 2019). "During experimental in vitro infection of permissive cell lines, VZV stimulates SOCS1 and, to a greater extent, SOCS3 in HaCaT human keratinocytes and MRC-5 human lung fibroblasts, and it also stimulates SOCS3 but not SOCS1 in THP-1 human monocytes." (PMID 31031749, 2019). "In transgenic rats overexpressing SOCS1 in the retina, however, intraocular HSV-1 (McKrae strain) infection is reduced or delayed compared with wild type rats." (PMID 31031749, 2019). "An RT-qPCR analysis showed that the SOCS1 transcript was rapidly induced following MHV-68 infection, peaking at 2–4 hours after infection, and being continuously expressed until around 25 hours." (PMID 30075008, 2018). "Expression of SOCS1 and SOCS3 were at least 2.5-fold higher in H5N1 virus-infected macrophages than in mock-infected cells at 6-h post infection." (PMID 29475453, 2018). "Of these molecules, RIG-I, MDA5, ATG5, SOCS1, SOCS3, INF-a, ISG15and ISG56 showed differences in expression levels at different time points after DENV-3 or DENV-3 ADE infection." (PMID 29566761, 2018). "Meanwhile, the expression levels of SOCS1, INF-a, ISG15, and ISG56 greatly increased 96 h after DENV-ADE infection." (PMID 29566761, 2018). "In our study, Tyrosine kinase 2 (TYK2, one of the JAKs) and its negative regulators SOCS1, SOCS3 as well as anti-apoptosis genes BCL-XL and PIM1 were differentially regulated by IRF7 during the H6N2 infection." (PMID 30356848, 2018). "Similar to the observations in N67 infection, IL10R, SOCS1, TRIM24, and PTGER2 were also inhibited in mice day 1 infected with 17XNL." (PMID 30327482, 2018). "Infection of IC-21 mouse macrophages or MEFs with SG-MCMV resulted in early, transient stimulation of SOCS1 and SOCS3 mRNA expression compared with medium-treated controls." (PMID 28182772, 2017). "IFN λ and SOCS-1 and SOCS-3 expression were evaluated at 12 h and 24 h following mock, RSV A2, rA2-GC12 and rA2-GC4 infections." (PMID 28671606, 2017).